MMP2 (matrix metallopeptidase 2)
Diseases named in the same sentence as MMP2 in open-access papers (continued):
Sharing a sentence is not in itself a finding about the gene and the disease.
demyelinating disease (1 paper, 2021). A broad group of disorders that affect the myelin sheaths that cover the neurons. "Interestingly, research has demonstrated that ITGB3 can regulate expression of matrix metalloproteinase 2 (MMP2), a protein that is critical in the inflammatory response and in demyelinating diseases, such as MS." (PMID 34831441, 2021).
dermatomyositis (1 paper, 2016). Dermatomyositis (DM) is a type of idiopathic inflammatory myopathy characterized by evocative skin lesions and symmetrical proximal muscle weakness. "Although, in some inflammatory myopathies, such as polymyositis, dermatomyositis, and inclusion body myositis, both MMP-2 and MMP-9 are upregulated, their balance depends on the type of disease and local presence of various factors." (PMID 28042204, 2016).
diverticulitis (1 paper, 2024). An infection that develops in the diverticula of the intestinal tract. "Whilst a collagen deficit does not identify individuals who will go on to develop diverticulitis, one study demonstrated downregulation of MMP2, MMP9 and MMP13 expression and an increase in MMP1, TIMP1 and TIMP3 in inflamed mucosa of patients with diverticulitis versus Crohn’s disease." (PMID 38831715, 2024).
Duchenne muscular dystrophy (1 paper, 2025). Duchenne muscular dystrophy (DMD) is a neuromuscular disease characterized by rapidly progressive muscle weakness and wasting due to degeneration of skeletal, smooth and cardiac muscle. "It has been known that matrix metalloproteinases, such as MMP-2 and MMP-9, play a critical role in the homeostasis and maintenance of myofiber functional integrity and that inhibition of MMP-9 improves myofiber regeneration in rodent models of Duchenne muscular dystrophy." (PMID 41009467, 2025).
ductal carcinomas of the breast (1 paper, 2015). "A recent paper by our group disclosed another gene of the same family, MMP2, as a key player in the progression of ductal carcinomas of the breast." (PMID 25391423, 2015).
duodenal ulcer (1 paper, 2023). An ulcer in the duodenal wall. "The MMP-2/TIMP-1 ratio was higher in patients with simultaneous gastric and duodenal ulcers (P < 0.05)." (PMID 37605137, 2023). "Furthermore, the presentation of the highest levels of MMP-2 and MMP-2/TIMP-1 ratio, along with the lowest levels of TIMP-1 in the coincidence of gastric and duodenal ulcer, raise the presumption of more severe infection in these patients." (PMID 37605137, 2023).
E. coli infection (1 paper, 2018). "In both PBMO and CBMO, E. coli infection increased the portion of MMP-9-expressing cells but did not have an effect on MMP-2 protein expression." (PMID 30524196, 2018).
endometrial adenocarcinoma (1 paper, 2024). "An in vitro study of the anti-tumor activity of curcumin in endometrial adenocarcinoma found that curcumin suppressed cancer cell migration, accompanied by a significant reduction in MMP-2 and MMP-9 protein expression." (PMID 39335164, 2024).
endometrial tumors (1 paper, 2023). "MMP2 and MMP9 downregulation and protein inhibition are desired effects, as their expression levels are closely related to invasion and metastasis, which also applies for endometrial tumors." (PMID 37313172, 2023).
endometritis (1 paper, 2025). An acute or chronic, usually bacterial infectious process affecting the endometrium. "The results demonstrate that oxidative-stress-mediated endometritis significantly upregulates MMP2, MMP9, and the TGFβ1/Smad3 pathway activity, while suppressing COL-IV expression." (PMID 40646747, 2025). "This study found upregulated expressions of TGFβ1, Smad3, and MMP2/9 during bovine endometritis." (PMID 40646747, 2025). "Additionally, the expression levels of matrix metalloproteinases MMP2 and MMP9 were significantly upregulated (p < 0.05) in the endometritis group." (PMID 40646747, 2025).
endophthalmitis (1 paper, 2025). An infectious process affecting the internal structures of the eye. "Multiple regression analysis revealed that the longer the duration of DM and the endophthalmitis diagnosis was associated with TIMP2/MMP2 ratio." (PMID 41009516, 2025). "Significantly, TIMP2 and TIMP2/MMP2 levels were highest in the endophthalmitis group, whereas MMP2 levels were highest in the dropped crystalline lenses group." (PMID 41009516, 2025). "Preoperative diagnostic pathology significantly influenced the levels of MMP2, and it was highest in patients with dropped IOL/crystalline lens followed by patients with endophthalmitis (19.2 ng/mL and 17.0 ng/mL, respectively, p = 0.03)." (PMID 41009516, 2025). "The TIMP2/MMP2 ratio varied significantly among groups (p = 0.004), being highest in the endophthalmitis group (6.49) and lowest in the dropped IOL/lens cases (1.46)." (PMID 41009516, 2025). "Furthermore, preoperative diagnostic retinal pathology significantly influenced the TIMP2/MMP2 ratio, in which the highest ratio was observed in patients with endophthalmitis (6.49) and the lowest ratio was observed in patients with dropped IOL/crystalline lens (1.46, p = 0.004)." (PMID 41009516, 2025).
enteritis (1 paper, 2021). Inflammation of the small intestine. "TAC, MMP-9 and MMP-2 estimations may be noteworthy in lamb enteritis diagnosis and monitoring of its therapeutic programs wherein TAC is the best among them." (PMID 34395600, 2021).
Epithelial Dysplasia (1 paper, 2014). "Mann Whitney U test, to compare the expression scores of MMP-2 and TIMP-2 of normal oral mucosa with epithelial dysplasia, was statistically significant (P < 0.001)." (PMID 24591757, 2014).
eumycetoma (1 paper, 2019). "Geneugelijk and colleagues demonstrated the presence of both MMP-2 and MMP-9 in eumycetoma lesions caused by M. mycetomatis." (PMID 31295246, 2019).
Fabry disease (1 paper, 2020). Fabry disease (FD) is a progressive, inherited, multisystemic lysosomal storage disease characterized by specific neurological, cutaneous, renal, cardiovascular, cochleo-vestibular and cerebrovascular manifestations. "Moreover, a correlation of MMP2 with MSSI and other signs of cardiomyopathy in Fabry disease were reported (LVH, LGE, diastolic dysfunction).Additionally, elevated levels of galectin-1 supported the significant role of extracellular matrix remodelling in Fabry disease." (PMID 33138098, 2020).
familial Alzheimer disease (1 paper, 2022). A degenerative disease of the brain that causes gradual loss of memory, judgment, and the ability to function socially. "Of note, human iPSCs from patients with sporadic Alzheimer’s disease (sAD) and familial Alzheimer’s disease (fAD) enhance MMP-2 and MMP-9 production, which leads to tau degradation, in both its monomeric and pathologically aggregated forms." (PMID 36232390, 2022).
femoral neck fracture (1 paper, 2026). Fractures of the short, constricted portion of the thigh bone between the femur head and the trochanters. "Clinical samples from SONFH patients and femoral neck fracture controls were analyzed for VEGF, Endostatin and MMP-2 expression." (PMID 41996352, 2026).
Fever (1 paper, 2023). Body temperature elevated above the normal range. "The concentration of MMP-2, MMP-3, MMP-9, MMP-13, TIMP-1, and FG-α in the KD group were significantly higher than those in the fever group (p < 0.05).The KD group was divided into two subgroups, patients with combined CAL and 179 patients without combined CAL." (PMID 37575991, 2023). "The concentration of MMP-2, MMP-3, MMP-9, MMP-13, TIMP-1, and FG-α in the KD group were significantly higher than those in the fever group (p < 0.05)." (PMID 37575991, 2023).
Focal cortical dysplasia (1 paper, 2022). A type of malformation of cortical development that primarily affects areas of neocortex. "Increased expression of MMP-2 was found in the brains of adult patients with focal cortical dysplasia (FCD) and hippocampal sclerosis (HS)." (PMID 36499038, 2022).
Follicular Cyst (1 paper, 2023). Cyst due to the occlusion of the duct of a follicle or small gland. "FGF7 regulated the PPAR signaling pathway (FABP5 and SCD) and the MAPK signaling pathway (FGF1, FGFR2, IL1A, TGFB1, and CSF1) and pathways in cancer (IL7, CD44, SMAD2, and MMP2) may be involved in the formation of follicular cysts." (PMID 38274662, 2023).
gastric cardia carcinoma (1 paper, 2013). A carcinoma that arises from epithelial cells of the cardia of stomach. "In addition, recent studies reported that a series of gene mutation such as adenosine diphosphate ribosyltransferase (ADPRT) and X-ray repair cross-complementing 1 (XRCC1), matrix metalloproteinases 2 (MMP-2), and cyclooxygenase-2 (COX-2) were only associated with the gastric cardia cancer." (PMID 23826241, 2013).
gastrointestinal mucositis (1 paper, 2022). "Our study has demonstrated that gastrointestinal mucositis induced by 5-FU increases the activity of the proteolytic enzymes MMP-1, MMP-2, MMP-8, and TIMP-1 in sera and tissues." (PMID 36290656, 2022).
Gaucher disease type 1 (1 paper, 2024). Gaucher disease type 1 is the chronic non-neurological form of Gaucher disease (GD; see this term) characterized by organomegaly, bone involvement and cytopenia. "In patients with Gaucher disease type 1, osteopontin positively correlated to bone disease domain (r = 0.28, p-value = 0.001) and GD-DS3 (r = 0.37, p-value < 0.001), while MMP-2 was positively correlated to GD-DS3 (r = 0.20, p-value = 0.022) but not to bone disease." (PMID 39590837, 2024).
geographic atrophy (1 paper, 2021). "Recent studies demonstrate significant differences in plasma concentrations of MMP-9, TIMP-1, and TIMP-3 proteins in patients with AMD: higher levels of TIMP-1 and MMP-9 in patients with geographic atrophy (GA) and lower levels of TIMP-3 and lower TIMP-3/MMP-2 ratios in patients with CNV." (PMID 35155457, 2021).
gingival enlargement (1 paper, 2024). "It has been suggested that azithromycin can improve DIGE by inhibiting cell proliferation and collagen synthesis and activating matrix metalloproteinases (MMP-1, MMP-2) in gingival fibroblasts from patients with Cyclosporine A-induced gingival enlargement." (PMID 39070408, 2024).
gingival fibromatosis (1 paper, 2021). "In ERS GFs, MMP2 protein and MMP2 mRNA level were 3-fold increased both at the protein (CM) and transcript levels (cell lysates) suggesting that increased expression of COL8A1 and MMP2 would contribute to the pathogenesis of gingival fibromatosis." (PMID 34777248, 2021).
gliosarcoma (1 paper, 2017). A rare histological variant of glioblastoma (WHO grade IV) characterized by a biphasic tissue pattern with alternating areas displaying glial and mesenchymal differentiation (WHO). "Further, MMP-2 and MMP-9 were shown to be distinctly expressed in mesenchymal tumor areas of gliosarcomas." (PMID 28234925, 2017).
herpes simplex encephalitis (1 paper, 2019). Herpes simplex virus encephalitis (HSE) is caused by the infection of the central nervous system by Herpes simplex virus (HSV) that could have a devastating clinical course and a potentially fatal outcome particularly with delay or lack of treatment. "In animal models of herpes simplex encephalitis, MMP-2 levels in CSF were high early in infection, as well as levels of MMP-9." (PMID 30777092, 2019).
histiocytic lymphoma (1 paper, 2017). "All the solid tumors, and histiocytic lymphoma cells produce MMP2 as inactive form." (PMID 29023465, 2017).
HIV dementia (1 paper, 2007). "Interestingly, the MMP-2 cleavage and inactivation of CXCL12 in the brain generates a potent and selective neurotoxin implicated in HIV dementia." (PMID 17375198, 2007).
HIV-associated neurocognitive disorder (1 paper, 2023). HIV-associated neurocognitive disorder (HAND) remains a common complication of HIV infection in the combination antiretroviral therapy (ART) era. "Regarding neurodegenerative disorders, only one study reported that individuals with the MMP2 −735CT genotype and −735T allele were at higher risk of developing HIV-associated neurocognitive disorders (HAND)." (PMID 37109410, 2023).
Hodgkins lymphoma (1 paper, 2007). A heterogeneous group of malignant lymphoid neoplasms of B-cell origin characterized histologically by the presence of Hodgkin and Reed-Sternberg (HRS) cells in the vast majority of cases. "Strong MMP-2 expression is correlated with a favorable prognosis of Hodgkin's lymphoma." (PMID 17559667, 2007).
hydatidiform mole (1 paper, 2009). A gestational trophoblastic disorder characterized by marked enlargement of the chorionic villi, hyperplasia of the villous trophoblastic cells and hydropic changes.
hyperostosis (1 paper, 2014). Excessive thickening of bone. "In addition, activated MMP-2 in hyperostotic lesions may change the physiological metabolism of the skull bone and, thus, be important for the formation of hyperostosis." (PMID 24959261, 2014).
hypersensitivity pneumonitis (1 paper, 2019). Hypersensitivity pneumonitis (HP) is a pulmonary disease with symptoms of dyspnea and cough resulting from the inhalation of an antigen to which the subject has been previously sensitized. "Two polymorphisms in the MMP1 and MMP2 genes are associated with the risk of hypersensitivity pneumonitis in the Mexican mestizo population." (PMID 31590404, 2019).
Hypoalbuminemia (1 paper, 2018). The concentration of albumin in the blood circulation is below the lower limit of normal. "Duodenal biopsy samples were taken from the four hypoalbuminemic CE dogs, and the correlations between mucosal pro- and active MMP-2 and-9 activities and hypoalbuminemia were evaluated." (PMID 29530095, 2018).
inflammatory skin disease (1 paper, 2024). Inflammatory skin disorders covers a broad category that includes many conditions ranging in severity, from mild itching to grave medical health complications These disorders are common in people of all ages and races. "Thus, MMP-2 and MMP-9 play important roles in inflammatory skin diseases." (PMID 39062816, 2024).
internal carotid artery stenosis (1 paper, 2022). Carotid stenosis is a narrowing or constriction of the inner surface (lumen) of the carotid artery, usually caused by atherosclerosis. "The authors’ research has shown a significant increase in MMP2 and MMP9 activity and a significant increase in the concentrations of claudin-1 and occludin in the blood of patients undergoing the reconstruction of internal carotid artery stenosis." (PMID 35627746, 2022).
interstitial lung disease (1 paper, 2014). A diverse group of lung diseases that affect the lung parenchyma. "MMP2 and MMP9 are the subgroup of MMPs that have been most extensively studied in interstitial lung diseases and their genes and proteins are upregulated in IPF." (PMID 25551570, 2014).
intrahepatic cholestasis (1 paper, 2022). A cholestasis characterized by impairment of the bile flow caused by obstruction located in the liver. "The inhibition of MMP-2 and MMP-9 activity in intrahepatic cholestasis of pregnancy ameliorated the biliary disease." (PMID 36551935, 2022).
ischemic cardiomyopathy (1 paper, 2013). Ischemic cardiomyopathy is a cardiomyopathy in which a weakness in the muscle of the heart due to inadequate oxygen delivery to the myocardium with coronary artery disease being the most common cause. "Our findings suggest that the relative contributions of these two MMP-2 isoforms are temporally distinct and that the NTT-MMP-2 isoform is a downstream mediator of a discrete subset of the phenotypic features characteristic of ischemic cardiomyopathy." (PMID 23874529, 2013).
juvenile Paget disease (1 paper, 2015). "Our results may also help clarify the etiology of the altered snouts of mice with mutations in genes known to affect resorption such as Mmp2, and jaw length defects in humans with conditions such as Juvenile Paget’s disease (i.e., Opg) and Spondyloepimetaphyseal dysplasia (i.e., Mmp13)." (PMID 26449912, 2015).
large cell carcinoma (1 paper, 2022). A malignant epithelial neoplasm composed of large, atypical cells. "This process is mediated by HMGA1-dependent upregulation of the matrix metalloproteinase-2 gene (MMP-2) which promotes migration and invasion of H1299 large-cell carcinoma cells." (PMID 35948739, 2022).
leptospirosis (1 paper, 2023). A contagious bacterial infection caused by spirochetes of the genus Leptospira. "No studies evaluating the role of TGF-β and MMP-2 in leptospirosis were identified in this review." (PMID 36700601, 2023).
leukoplakia (1 paper, 2014). A white patch or plaque on a mucous membrane that cannot be characterized clinically or pathologically as any other disease. "In this study we sought to determine the expression and the correlation of MMP-2 and TIMP-2 in oral leukoplakia through different grades of oral epithelial dysplasia as these proteases appear to be important in the early phases of cancer progression including local invasion and micrometastasis." (PMID 24591757, 2014).
lichen planus (1 paper, 1998). A chronic, recurrent, pruritic inflammatory disorder of unknown etiology that affects the skin and mucus membranes. "Using zymography, elevated levels of MMP-2 and MMP-9 were observed in carcinoma samples in comparison with lichen planus or normal oral mucosa." (PMID 9649139, 1998).
Lipedema (1 paper, 2020). Disorder of adipose tissue characterized by symmetric and bilateral enlargement of the lower extremities due to abnormal deposition of subcutaneous fat often in obese women. "We analyzed the expression of the primary adipogenic (ADIPOQ, LPL, PPAR-γ and Glut4) and ECM-remodeling (collagen, FN, LN, ITAGA5, MMP2, 9 and 11) markers at the transcriptional level and by immunohistochemistry in 3D spheroids derived from ASCs from both lipedema and healthy individuals." (PMID 33171717, 2020). "The data show a decrease in gene expression of MMP2, MMP9 and MMP11 in lipedema-differentiated spheroids as compared to lipedema-undifferentiated and healthy spheroids." (PMID 33171717, 2020).
lipid metabolism disorders (1 paper, 2024). "In women, matrix metalloproteinases, specifically MMP-2 and MMP-9, could become markers of lipid metabolism disorders." (PMID 39769504, 2024).
lipidosis (1 paper, 2017). "Moreover, adipocytokines IL6 and Leptin, in addition the genes, EGR1, FOS, SERPINE1, AGT and MMP2 might have great impacts on adipocyte differentiation and lipidosis." (PMID 28706200, 2017).
Listeria infection (1 paper, 2019). "This pro-Infliximab is selectively activated by disease-associated MMP-2/9 in the RA region and shows similar PKs and therapeutic efficacy as Infliximab without dysregulating systemic immunity against Listeria infection in vivo." (PMID 31194726, 2019).
lung neoplasm (1 paper, 2023). A benign or malignant, primary or metastatic neoplasm involving the lungs. "Within the -735CC genotype, we observed the highest MMP-2 concentration in the smoking control (x ̄ = 216.56 ng/mL) and the lowest in patients with other lung neoplasms (x ̄ = 138.05 ng/mL)." (PMID 37445754, 2023). "In contrast, we observed lower concentrations of MMP-2 in patients with other lung neoplasms and the -735CC genotype (x ̄ = 138.05 ng/mL), than in patients with other lung neoplasms and the -735CT genotype (x ̄ = 164.48 ng/mL) at the limit of statistical significance (p = 0.060294)." (PMID 37445754, 2023).
lymphangioleiomyomatosis (1 paper, 2021). A multifocal neoplasm with perivascular epithelioid cell differentiation affecting almost exclusively females of child-bearing age. "In lymphangioleiomyomatosis (LAM), a pulmonary rare disease, MMP-2 and MMP-9 have been detected at high levels in serum and urine." (PMID 34944575, 2021).